CD4 (CD4 molecule)
Diseases named in the same sentence as CD4 in open-access papers (continued):
Sharing a sentence is not in itself a finding about the gene and the disease.
leprosy (continued). "The leprosy protective allele, rs2015583:G, is associated with reduced ACTR1A expression in CD4+ T cells (p = 4.69 × 10−9, β = −0.085)." (PMID 36121873, 2022). "A retrospective study was conducted in French Guiana, including patients living with HIV (PLHIV) with advanced infection (CD4 < 200/mm3) and developing leprosy or a leprosy reaction within six months of HAART initiation, from 2000 to 2020." (PMID 35245291, 2022). "Our leading candidate mediator of leprosy risk at 10q24.32, ACTR1A expression in CD4+ T cells, is highly biologically plausible as a determinant of leprosy." (PMID 36121873, 2022). "In MB leprosy patients, Treg (CD4+CD25+) is thought to play an unresponsive role in dealing with M. leprae (M. leprae specific unresponsiveness)." (PMID 33708252, 2021). "In a BT-like murine model of leprosy, IL-10 suppression significantly augmented M-leprae-specific CD4+ and CD8+ T cell infiltration and permitted CD4+ T cells to penetrate and fragment nerve tissue." (PMID 34746168, 2021). "In order to evaluate T cell counts, leprosy–HIV co-infected individuals were evaluated to quantify their CD3+/CD4+T cell populations." (PMID 32849508, 2020). "In summary, our present study for the first time reports that CD4+IL6R+ T cells are involved in IL-17A production in T1R leprosy patients." (PMID 32934336, 2020). "Secondly, M. leprae (MLSA) antigen activates IL-6R to produce IL-17A by CD4+ T cells from T1R leprosy patients." (PMID 32934336, 2020). "The attribute IL-4+ CD8+ T-cells was a general biomarker to identify both Household contacts, whereas IL-4+ CD4+ T-cells was a general biomarker for both subgroups of Leprosy patients." (PMID 33341111, 2020). "PBMCs from leprosy patients and healthy individuals were stimulated with antigens and stained with fluorochrome conjugated anti-CD4 antibody to intracellular cytokines." (PMID 30642265, 2019). "Analyzed results were presented as mean percentage of cytokines expressing CD4+ T cells in blood of healthy individuals and leprosy patients." (PMID 30642265, 2019). "Basal mean percentage of IL-4 expressing CD4+ T cells was significantly higher (p = 0.0008) in PBMCs of lepromatous leprosy patients as compared to healthy individuals." (PMID 30642265, 2019). "Mean percentage of pSTAT-6 expressing CD4+ T cells was compared among leprosy patients and healthy individuals." (PMID 30642265, 2019). "Although CD4 T cells are the primary determinant of outcome of M. leprae infection/ leprosy, we also assessed the CD8 T cell response." (PMID 30631322, 2018). "We first showed that CD4+CD25− converted into CD4+CD25+ cells when cocultured with CD19+ cells derived from leprosy patients." (PMID 30083152, 2018). "The percentage of CD4+Foxp3+ Tregs also enhanced in the presence of leprosy derived Bregs, which indicated that Bregs not only converted the T effector into Tregs itself but also enhanced the Tregs activity." (PMID 30083152, 2018). "Cell coculture results showed that purified Bregs cells from leprosy patients convert CD4+CD25− cells into CD4+CD25+ cells." (PMID 30083152, 2018). "Vaccine immunogenicity studies for both leprosy and TB vaccine candidates have mostly focused on their ability to induce type-1 cell-mediated immunity, particularly CD4+ Th cells releasing type 1 helper (Th1) cytokines." (PMID 29535713, 2018). "CD4+CD25+ Tregs were known to have a crucial role in the regulation of leprosy disease development and suppression of host immune response according to previous studies." (PMID 30083152, 2018). "Taken together, these results suggested that CD19+ B cells of leprosy patients (BT and BL/LL) converted T effector (CD4+CD25−) cells into Tregs (CD4+CD25+)." (PMID 30083152, 2018). "CD19+ B cells derived from healthy controls, tuberculoid leprosy patients (BT), and lepromatous leprosy patients (BL/LL) were cocultured with CD4+CD25− cells (T effector cells) isolated from healthy controls." (PMID 30083152, 2018).
leprosy (continued). "CD4+ Th17 cells have been recently identified in borderline cases of leprosy, which highlighted their importance in infectious diseases as well." (PMID 29686668, 2018). "CD4+ T-cell responses are also critical in mycobacterial infections, such as has been described for leprosy and tuberculosis." (PMID 28449694, 2017). "A recent work on leprosy identified CD4+ Th17 Cells in borderline cases and highlighted their importance in infectious diseases as well." (PMID 26751584, 2016). "In conclusion, Th17 cells with intracellular IL-17A, F are increased in both types of leprosy reactions whereas CD4+IL-21+ cells were higher only in ENL reactions patients." (PMID 27035913, 2016). "In conformity with our earlier reports antigen stimulated PBMC of both types of leprosy reactions also showed IL-17 to be present in CD4+CCR6+ cells, along with the signature transcription factor RORC and pSTAT3." (PMID 27035913, 2016). "In this situation, subclinical leprosy is revealed due to the restoration of CD4 lymphocytes leading to tissue infiltration and inflammation resembling a T1R." (PMID 26267882, 2015). "CD8+ population of T cells with CD25+FOXP3+ were lower than the CD4+ T cells in both leprosy types and healthy contacts." (PMID 24454972, 2014). "We have demonstrated for the first time that multibacillary leprosy patients under 15 years old have greater CD4+ and CD8+ Treg frequencies and these correlate with clinical and laboratorial aspects of disease." (PMID 24244424, 2013). "In conclusion, it would appear that Th17 cells form a third Th subset of CD4+ effector cells in leprosy in addition to the Th1 and Th2 types." (PMID 23936569, 2013). "In this study, we showed that in individuals under 15 years old, the numbers of CD4+CD25highFOXP3+ cells and their activated fraction, CD4+CD25highFOXP3high cells, were higher in MB leprosy patients compared to HHC." (PMID 24244424, 2013). "All HIV/leprosy-coinfected individuals showed a reduction in CD4+ cells, as expected for HIV- positive individuals, although the median values were similar or higher than those shown in other studies, regardless of viral load levels and/or HAART status." (PMID 22205964, 2011). "An increase in absolute CD4+ T counts was observed in HIV/leprosy coinfected patients with undetectable VL levels, reflecting the quantitative immune reconstitution that occurs as a consequence of viral replication control and antiretroviral therapy." (PMID 22205964, 2011). "But, this fact was in lines with the earlier data, which showed co-localization of granulysin and CD4+ T cells in tuberculoid leprosy lesions." (PMID 22132248, 2011). "In (C), activated CD4+ T cells can further differentiate by means of the type of phenotype of the recruited macrophage (M1 or M2/M4) into distinct T helper subpopulations according to the severity of the leprosy clinical form." (PMID 39308868, 2024). "Taken together our results indicated that PD-1 expression on CD4+CD25+FoxP3+ cells increased in leprosy patients, it may contribute to immunosuppression of the host." (PMID 37153623, 2023). "IL-17 producing CD4+ T cells have been considered as an independent subtype of helper T cells, which contribute to maintain the stability of leprosy and promote inflammation in leprosy reactions." (PMID 36389696, 2022). "In contrast, there was a little difference in the frequency of CD4 T cells between healthy skin and TT and LL leprosy patients, although there was indeed an increase tendency in TT leprosy patient group, which may be due to limited samples in this study." (PMID 36389696, 2022). "Dermal γδ T cells were approximately 30% IL-17A+ in TT leprosy and in LL were nearly 20%, whereas the fraction for CD4+ T cells was only about 20% in TT groups with even lower percentage in LL groups, indicating higher fraction of IL-17A+ in γδ T cells than in CD4 T cells." (PMID 36389696, 2022). "CD4+ IL-17+ cells participate in immunoregulation and are increased after leprosy treatment." (PMID 34932761, 2021).
leprosy (continued). "Gene expression of isolated CD4+ T cells of leprosy patients (NR vs T1R) were analyzed for 21 signature genes of Th17 lineage and associated molecules with a rationale to understand the differences between the immunopathology/inflammation associated with localized T1R reactions via qPCR assay." (PMID 32934336, 2020). "A total of 132 lepromatous leprosy patients and 120 healthy controls were analyzed for IL-10 cytokine gene polymorphisms using PCR-SSP assay and flow cytometry was used to analyze IL-10 secretion by CD4 and Tregs in various genotype of leprosy patients." (PMID 32849660, 2020). "However, all the three antigens induced increase in IFN-γ expressing CD4+T cells in healthy individuals and tuberculoid leprosy patients than in LL patients which is in contrast to findings observed by ELISA." (PMID 30642265, 2019). "This concept is highlighted in a leprosy-specific study, where IL-10+ produced by Treg cells in BL/LL patients correlates significantly with polarized immunity highlighted by lesser IL-17 by CD4+ T cells in the same group." (PMID 29686668, 2018). "Despite it being well-established that CD4 T cells are critical determinants of leprosy presentation, this is the first study that has assessed the presence of M. leprae–specific multifunctional T cells in leprosy patients and controls." (PMID 30631322, 2018). "In fact, the diagnosis of leprosy in patients with HIV infection has been associated with the improvement of patient immunity after the initiation of HAART and was characterized by elevated CD4 + T cells in these patients." (PMID 30020931, 2018). "CD4+ subsets of Th17 cells and CD25+FOXP3+ regulatory T cells (Tregs) have been shown to play a major role in disease associated immunopathology and in stable leprosy as reported by us and others." (PMID 27035913, 2016). "Recently, the mechanism of action of FoxP3 in CD4+CD25+ T cells derived from BL/LL leprosy patients was shown to result from increased molecular interactions of FoxP3 with Histone deacetylases (HDAC7/9) in the nucleus of CD4+CD25+ T cells derived from BL/LL patients." (PMID 24722473, 2014). "Taken together the data indicates that in addition to IFN-γ producing Th1 cells, CD4+IL-17+ cells have a role in the adaptive immune response in the more resistant form of tuberculoid leprosy and discriminate between the clinical types of leprosy." (PMID 23936569, 2013). "Moreover, despite the presence of M. leprae, HIV/leprosy coinfection exhibited the same CD4+ T cell behavior observed in HIV-infected patients in the absence of detectable VL under HAART, consistent with previous studies." (PMID 22205964, 2011). "In HIV-monoinfected and HIV/leprosy coinfected individuals with high viremia, CD4+ T cell depletion together with pronounced T cell activation may be involved in a generalized hyporesponsiveness of the immune system." (PMID 22205964, 2011). "While IL-17A is produced by CD4+ Th17 cells, it is involved in neutrophilia, inflammation, tissue destruction, and repair through the control of regulatory molecules (programmed death-1/programmed death ligand-1) and is also related to reverse reaction (RR) episodes in leprosy patients." (PMID 36142557, 2022). "Anti-CD28/CD49d were used in all the culture of mononuclear cells as costimulatory molecules and to test whether Tregs influence development of leprosy reactions, we analyzed CD4+ and CD8+ Treg cells, defined as CD25+Foxp3+, in multibacillary patients, T1R, T2R and HV." (PMID 35924037, 2022). "CD4 and CD8 T cells have been implicated in the protective immune response against mycobacteria and might, therefore, account for the improvement in their protective response against leprosy." (PMID 28467415, 2017). "In conclusion, our study showed the participation of TGF-β producing CD4+ and CD8+ Treg in the maintenance of a hyporesponsive profile in multibacillary leprosy patients." (PMID 35924037, 2022).
leprosy (continued). "In this context, our results show the involvement of TGF-β producing CD4+ and CD8+ Treg in maintenance of the hyporesponsive response in multibacillary leprosy patients favoring Mycobacterium leprae survival." (PMID 35924037, 2022). "Our results showed a decrease in CD4+TGF-β+ Treg and CD8+ TGF-β+ Treg in leprosy multibacillary patients during both types of reactional episodes." (PMID 35924037, 2022). "Percentage of IL-10 producing Treg cells (CD4 + CD25 +) was significantly higher among TT genotypes in leprosy patients compared to that of CC and CT genotypes of leprosy patients (P = 0.0003)." (PMID 32849660, 2020). "Short-term cultures in vitro of peripheral blood mononuclear cells from leprosy patients and healthy Controls were carried out to quantify the percentages of cytokine+ cells (IFN-γ, IL-4 and IL-10) amongst T-cells, CD4+ T-cells and CD8+ T-cells." (PMID 33341111, 2020). "There are several immunological events that seem to influence the outcome of leprosy, including mechanisms mediated by CD8+ and CD4+ T-cells." (PMID 33341111, 2020). "The main goal of the present study was to characterize the global cytokine signatures of CD4+ and CD8+ T-cells from leprosy patients with distinct clinical forms and their respective household contacts (HHC) upon in vitro antigen-specific stimuli." (PMID 33341111, 2020). "We also observed the simmiler pattern of IL-10 production by CD4+CD25– cells in various genotypes (CC, CT and TT) of leprosy patients." (PMID 32849660, 2020). "We found BL/LL derived CD19+ B cells induced PD-1 (p < 0.0005) expression in CD4+CD25− cells, CD19+ B cells isolated from BT leprosy (p < 0.0005) as compared to healthy controls." (PMID 30083152, 2018). "The higher proportions of triple+ and double+ CD4 and CD8 T cells in HHC, alongside reports from other disease and vaccine studies, implicates these cells in protection against leprosy development." (PMID 30631322, 2018). "We observed that significant number of T effector cells (CD4+CD25−) were converted into CD4+CD25+ Tregs when CD4+CD25− cells were cocultured with CD19+ B cells isolated from BT (4.11 ± 1.12%, p < 0.005) and BL/LL leprosy (12.61 ± 2.18%, p < 0.0005) patients." (PMID 30083152, 2018). "Using multiparameter flow cytometry we observed that MLCS, PPD and ML2028 were recognized by larger populations of antigen-specific multifunctional CD4 T cells in control and HHC than in leprosy patients." (PMID 30631322, 2018). "Flow cytometry results showed that the expression of FoxP3 in CD4+CD25+ cells Treg significantly increased (p < 0.0005) when leprosy derived (BT, BL/LL) CD19+ B cells cocultured with Tregs (CD4+CD25+)." (PMID 30083152, 2018). "Previous work in leprosy and tuberculosis has revealed the major role played by interferon-γ (IFN-γ), an effector cytokine produced by pathogen-specific memory CD4 T cells, in the control of the infection by these intracellular pathogens." (PMID 28467415, 2017). "In order to identify the Treg cells in human leprosy, immunophenotyping was done for the markers CD4, CD25 and FoxP3 on PBMCs derived from leprosy patients (BT/TT vs. BL/LL) (n = 15 in each group) and healthy contacts (HCs, n = 10)." (PMID 26751584, 2016). "This is the first work investigating CD4+ and CD8+ Treg in leprosy patients and HHC under 15 years old." (PMID 24244424, 2013). "We evaluated the frequency of CD4+/CD8+CD25highFOXP3+ and CD4+/CD8+CD25highFOXP3high cells in leprosy patients and household contacts, in both cases under 15 years old." (PMID 24244424, 2013). "For CD4+ T cells, frequency differences among CD45RA+ circulating cells were observed only when comparing groups 1 and 2 of the HIV/leprosy patients (medians: 22.4%, versus 37.7%; p<0.05), with the latter group showing a higher percentage of circulating cells." (PMID 22205964, 2011). "As expected, absolute counts of the CD4+ and CD8+ T cells from the HIV-infected individuals changed in relation to those of the leprosy patients and controls." (PMID 22205964, 2011).
leprosy (continued). "Cotrimoxazole preventive therapy was not initiated as the patient was already on dapsone for leprosy, and her CD4 count was within normal limits." (PMID 39229388, 2024). "Hence, the reduced frequency ofCD4+Tregs and the increased CD4+/CD8+ T cells ratio in untreated T2LR patients may explain the possibility of induction of excessive immune activation owning to the pre-existing high load of bacterial antigens in patients with lepromatous leprosy." (PMID 38130570, 2023). "A rise in Th17 cells was seen in patients of both types of reactional leprosy in comparison to the non-reactional ones with identical symptoms, as demonstrated by the presence of IL-17F and IL-17A in CD4 cells." (PMID 37809252, 2023). "Hence, we correlate the PD-1 expressing CD3, CD4, CD8 cells, resting T cells, activated T cells and Tregs with bacteriological index (BI) in leprosy patients." (PMID 37153623, 2023). "IRIS associated with leprosy reaction (T1R or T2R) occurred 2 weeks earlier than non-reactive leprosy (8 weeks versus 10 weeks), probably as part of a stronger immune response reflected by a greater increase in CD4 count (median fold increase: +0.7)." (PMID 35245291, 2022). "To date, it is known that in co-infected patients, the frequency of FOXP3+ cells does not seem to be influenced by the clinical type of leprosy, the CD4+ T cell count in the peripheral blood, or the HIV viral load." (PMID 34748560, 2021). "It was suggested that the frequency of FOXP3+ cells in the skin was not influenced by the clinical type of leprosy, CD4+ T cell count, or HIV viral load." (PMID 34748560, 2021). "There was a positive correlation between cell count and viral load, while there was a negative correlation between cell count and CD4, considering the presence of a leprosy reaction." (PMID 34748560, 2021). "Isolated CD4+ T helper cells were investigated in 19 of each Type 1 reactions (T1R) patients and non-reactions (NR) leprosy patients by Real Time PCR (qPCR) for RNA estimation." (PMID 32934336, 2020). "Specifically, increased antibody response, higher levels of lymphocyte activation (expression of CD25 by CD4+ and CD8+ T-cells) along with enhanced frequency of monocytes circulating in the peripheral blood were observed in leprosy patients as compared to contacts." (PMID 33341111, 2020). "In the present study, we have characterized the functional cytokine signatures of CD4+ and CD8+ T-cells from leprosy patients with distinct clinical forms and their respective household contacts (HHC), using a model of in vitro antigen-specific stimuli for peripheral blood mononuclear cells." (PMID 33341111, 2020). "Our data demonstrated that leprosy patients presented an overall polyfunctional profile of T-cells subsets, with increased frequency of IFN-γ+ T-cell subsets along with IL-10+ and IL-4+ from CD4+ T-cells." (PMID 33341111, 2020). "The cytokine signature analysis demonstrated that leprosy patients presented a polyfunctional profile of T-cells subsets, with increased frequency of IFN-γ+ T-cell subsets along with IL-10+ and IL-4+ from CD4+ T-cells, as compared to health Controls (Venn diagram report)." (PMID 33341111, 2020). "Moreover, it has been proposed that the degree of activation of CD4+ and CD8+ T-lymphocytes can also allow the discrimination between leprosy patients and their household contacts." (PMID 33341111, 2020). "Hence, the reduced frequency of CD4+Tregs and the increased CD4+/CD8+ T-cells ratio in untreated patients with ENL may explain the possibility of induction of excessive immune activation owning to the pre-existing high load of bacterial antigens in patients with lepromatous leprosy." (PMID 28991896, 2017). "In our study on leprosy, significantly higher frequency of IL-17+ was found on CD4+CD45RO+ cells in BT/TT (P = 0.0005) as opposed to BL/LL patients." (PMID 26751584, 2016).